HBS1L (HBS1 like translational GTPase)
Description:
GTPase component of the Pelota-HBS1L complex, a complex that recognizes stalled ribosomes and triggers the No-Go Decay (NGD) pathway. The Pelota-HBS1L complex recognizes ribosomes stalled at the 3' end of an mRNA and engages stalled ribosomes by destabilizing mRNA in the mRNA channel. Following mRNA extraction from stalled ribosomes by the SKI complex, the Pelota-HBS1L complex promotes recruitment of ABCE1, which drives the disassembly of stalled ribosomes, followed by degradation of damaged mRNAs as part of the NGD pathway.
Synonyms: HBS1; KIAA1038; ERFS; HSPC276; DKFZp434g247; EF-1a; eRF3c
Tractability: Small molecule: a structure with a bound ligand is known. PROTAC: ubiquitination databases record sites on it; its protein half-life has been measured.
Target class: Enzyme; Hydrolase
Gene: Protein-coding gene on chromosome 6 (134,960,378 to 135,103,056, reverse strand). Ensembl gene ENSG00000112339.
Subcellular location: Cytoplasm; Cytoplasm (Isoform 2)
Subcellular location (Human Protein Atlas): Cytosol; Nuclear bodies
Pathways (Reactome):
Metabolism of RNA: mRNA decay by 3' to 5' exoribonuclease
Metabolism of proteins: PELO:HBS1L and ABCE1 dissociate a ribosome on a non-stop mRNA
Gene Ontology:
Molecular function: protein binding; GTP binding; GTPase activity
Biological process: nuclear-transcribed mRNA catabolic process, no-go decay; rescue of stalled ribosome; ribosome disassembly; signal transduction; translation; negative regulation of gene expression
Cellular component: cytoplasm; cytosolic ribosome; Dom34-Hbs1 complex; extracellular exosome; membrane; cytosol
Genetic constraint (gnomAD): Loss-of-function variants: 25 observed, 44.38 expected, observed/expected ratio (o/e) 0.56, 90% interval 0.41 to 0.79. The upper end of that interval is the gene's LOEUF score, 0.79, which puts it in group 3 of 6, group 1 being the genes least tolerant of losing a copy. Missense variants: 483 observed, 536.16 expected, observed/expected ratio (o/e) 0.9, 90% interval 0.83 to 0.97. Synonymous variants: 183 observed, 199.53 expected, observed/expected ratio (o/e) 0.92, 90% interval 0.81 to 1.04.
Homologues: Orthologues: chimpanzee HBS1L (99% identical), macaque HBS1L (98% identical), dog HBS1L (92% identical), rat Hbs1l (89% identical), mouse Hbs1l (89% identical), guinea pig HBS1L (78% identical), tropical clawed frog hbs1l (74% identical), pig HBS1L (72% identical), zebrafish hbs1l (71% identical), Drosophila melanogaster HBS1 (48% identical), Caenorhabditis elegans hbs-1 (36% identical). Paralogues in human: GSPT1 (21% identical), GSPT2 (20% identical), EEF1A2 (20% identical), EEF1A1 (19% identical), EIF5B (17% identical), EEFSEC (17% identical), GFM1 (15% identical), EFL1 (14% identical), MTIF2 (14% identical), TUFM (14% identical), EFTUD2 (14% identical), GTPBP1 (13% identical), and 6 more.
Diseases named in the same sentence as HBS1L in open-access papers:
HBS1L is named in the same sentence as 30 diseases in open-access papers, as found by Europe PMC text mining. Sharing a sentence is not in itself a finding about the gene and the disease. The quoted sentences say what the papers report.
sickle cell disease (8 papers, 2013 to 2026). Sickle cell anemias are chronic hemolytic diseases that may induce three types of acute accidents: severe anemia, severe bacterial infections, and ischemic vasoocclusive accidents (VOA) caused by sickle-shaped red blood cells obstructing small blood vessels and capillaries. "Alternatively, HBS1L knockdown provided a potential target for treating β-thalassemia as well as other hemoglobinopathies such as sickle cell disease." (PMID 36888630, 2023). "In sickle cell disease patients, the HbF level elevation is associated with three quantitative trait loci (QTLs), BCL11A, HBG2 promoter, and HBS1L-MYB intergenic region." (PMID 28280727, 2017). "Fetal hemoglobin association results for SNPs at the BCL11A, HBS1L-MYB, and beta-globin loci in the CSSCD and the Cameroon sickle cell Anaemia cohort." (PMID 24667352, 2014). "Genetic variants at three quantitative trait loci (QTL) for fetal haemoglobin (HbF), BCL11A, HBS1L-MYB and the β-globin gene cluster, have attracted interest as potential targets of therapeutic strategies for HbF reactivation in sickle cell anaemia (SCA)." (PMID 29879141, 2018).
thalassemia (5 papers, 2013 to 2025). An inherited blood disorder characterized by a decreased synthesis of one of the polypeptide chains that form hemoglobin. "On average, we found a reduction of HBS1L mRNA expression of 71% in β0-thalassemia/HbE patients and 84% in healthy donors." (PMID 36888630, 2023). "The most studied genetic modifiers affecting the severity of SCD are the level of HbF expression, BCL11A, HBS1L-MYB, and coinheritance of α-thalassemia." (PMID 23762099, 2013).
hemoglobinopathies (4 papers, 2010 to 2024). "As anticipated, the HBB cluster, BCL11A, and the HBS1L-MYB intergenic region were consistently found to be associated with HbF changes in the included studies across all disease groups (i.e., non-hemoglobinopathy, SCD, β-thalassemia trait), involving a substantial number of SNPs." (PMID 39518961, 2024). "Concluding, the assays developed can be successfully applied for accurate, time and cost efficient simultaneous genotyping of SNPs associated with HbF levels in the BCL11A gene and in the HBS1L-MYB intergenic region in HPFH, β-thalassaemia, SCD or other hemoglobinopathy populations." (PMID 24502199, 2014). "In addition, about 15% of the HbF variance was explained by a polymorphism in BCL11A on 2p15, 19% by an intergenic variant in HBS1L-MYB on 6q23, and 10% by Xmn1 in Europeans without hemoglobinopathies." (PMID 20353593, 2010).
developmental delay (3 papers, 2019 to 2025). "For instance, Hbs1L deficiency, which affects Pelo levels and ribosome recycling, is associated with congenital anomalies and developmental delays, though this is linked to HBS1L mutations rather than PELO itself." (PMID 40785597, 2025).
anemia (2 papers, 2021 to 2022). A reduction in the number of red blood cells, the amount of hemoglobin, and/or the volume of packed red blood cells. "A HBS1L-MYB intergenic region variant associates both with increased risk of iron overload and reduced risk of iron deficiency anemia." (PMID 33536631, 2021). "HBS1L-MYB is an intergenic region that increases HbF values in thalassemia and sickle cell anemia and thus ameliorates anemia." (PMID 35741184, 2022). "HBS1L-MYB is also a main regulator of erythropoiesis, and its expression may improve anemia in patients who have renal failure with the presence of rs7776054 and rs6650371 SNPs." (PMID 35741184, 2022).
myeloproliferative neoplasm (2 papers, 2015 to 2017). A clonal hematopoietic stem cell disorder, characterized by proliferation in the bone marrow of one or more of the myeloid (i.e., granulocytic, erythroid, megakaryocytic, and mast cell) lineages. "Germline variations at JAK2, TERT, HBS1L-MYB and MECOM have been found to associate with myeloproliferative neoplasms (MPNs) in European populations." (PMID 29100304, 2017).
ovarian carcinoma (2 papers, 2020 to 2021). A malignant neoplasm originating from the surface ovarian epithelium. "At the same time, the high expression of FAM76A and HBS1L also suggested poor survival in ovarian cancer patients." (PMID 32998774, 2020). "GSEA was performed to determine a potential mechanism for HBS1L and FAM76A involved in ovarian cancer." (PMID 32998774, 2020).
allergic disease (1 paper, 2022). An immune response that occurs following re-exposure to an innocuous antigen, and that requires the presence of existing antibodies against that antigen. "Our study newly identified six loci associated with allergic diseases (MIIP, CXCR4, SCML4, CYP1B1, ICOS and LINC00824) and four pleiotropic loci associated with both autoimmune and allergic diseases (PRDM2, G3BP1, HBS1L and POU2AF1)." (PMID 35753705, 2022). "We identified four loci shared between the six autoimmune and allergic diseases (rs10803431 at PRDM2, OR=1.07, p=2.3×10−8, rs2053062 at G3BP1, OR=0.90, p=2.9×10−8, rs2210366 at HBS1L, OR=1.07, p=2.5×10−8 in Japanese and rs4529910 at POU2AF1, OR=0.96, p=1.9×10−10 across ancestries)." (PMID 35753705, 2022).
Hodgkins lymphoma (1 paper, 2018). A heterogeneous group of malignant lymphoid neoplasms of B-cell origin characterized histologically by the presence of Hodgkin and Reed-Sternberg (HRS) cells in the vast majority of cases. "For SNP rs6930223, located in the HBS1L-MYB region and a known eQTL for HBS1L, the allele increasing GM-CSF-producing CD8+ cells is protective against Hodgkin’s lymphoma." (PMID 30332657, 2018).
iron overload (1 paper, 2021). "Furthermore, the rs9399136[C] variant at the HBS1L/MYB locus is protective against IDA while increasing the risk of iron overload." (PMID 33536631, 2021). "The rs9399136[C] variant in the intergenic HBS1L/MYB region is the only variant to associate with both IDA (OR = 0.84 [0.80–0.89], P = 4.7 × 10−11) and iron overload (OR = 1.13 [1.07–1.20], P = 1.4 × 10−5)." (PMID 33536631, 2021).
leukemia (1 paper, 2023). A malignant (clonal) hematologic disorder, involving hematopoietic stem cells and characterized by the presence of primitive or atypical myeloid or lymphoid cells in the bone marrow and the blood. "Strikingly, the loss of HBS1L, exclusive to Early-Pro leukemias, was associated with extremely poor prognosis." (PMID 37337105, 2023). "HBS1L deletions were also only found in Early-Pro leukemias (n = 12/23, 52%; P = 1.5 × 10−5)." (PMID 37337105, 2023).
liver fibrosis (1 paper, 2024). "This association implies a potential relationship between the HBS1L and its protective effect on liver fibrosis through anti-inflammation." (PMID 39578894, 2024).
Nephropathy (1 paper, 2024). A nonspecific term referring to disease or damage of the kidneys. "Polymorphisms in genes such as BCL11A and HBS1L-MYB have been identified as key regulators of HbF production, offering potential targets for therapeutic modulation and personalized management of nephropathy in SCD patients." (PMID 38791464, 2024).
polycythemia vera (1 paper, 2017). "Furthermore, the risk alleles of MECOM rs2201862 and HBS1L-MYB rs9376092 were demonstrated to be negatively associated with the risk of developing polycythemia vera." (PMID 29100304, 2017).
renal failure (1 paper, 2015). "We show that even mild renal failure blunts erythropoietin production and propose the HBS1L-MYB locus as a regulator of erythropoietin." (PMID 25915923, 2015).
retinal degeneration (1 paper, 2024). Degeneration of the retina. "Taken together, these findings suggest that loss of Hbs1l leads to retinal degeneration due to premature death of photoreceptor cells." (PMID 38966981, 2024). "In this study, we report that loss of HBS1L results in retinal degeneration in both a human patient and Hbs1ltm1a/tm1a (hypomorph) mice." (PMID 38966981, 2024). "In summary, we report that genetic deficiency of HBS1L causes retinal degeneration in both a human patient and Hbs1ltm1a/tm1a mice." (PMID 38966981, 2024).
tumor (2 papers, 2019 to 2026). "Knockdown by siRNA of either WDSOF1 or HBS1L was synthetic lethal in a KRAS-driven tumor model." (PMID 31660150, 2019).
cancer (1 paper, 2024). A tumor composed of atypical neoplastic, often pleomorphic cells that invade other tissues. "In the first enriched pathway, surveillance pathway, five genes (HBS1L, DAZAP1, RBM8A, CSTF3, and CSTF2T) overlap, all of which have been previously implicated in cancer progression." (PMID 38305998, 2024).
HBS1L also shares sentences with these, for which no sentence is quoted: Retinal dystrophy (2 papers); viral diseases (2); colorectal cancer (1); cyst (1); gastric cancer (1); infection (1); inflammatory bowel disease (1); Iron deficiency anemia (1); lymphoma (1); male infertility (1); non-alcoholic fatty liver disease (1); renal cell carcinoma (1).